Y_RNA (Y RNA )
Gene: Miscellaneous RNA gene on chromosome 21 (39,344,537 to 39,344,628, forward strand). Ensembl gene ENSG00000252915.
Homologues: Orthologues: chimpanzee Y_RNA (100% identical). Paralogues in human: Y_RNA (80% identical), RNY3 (79% identical), RNY3P1 (79% identical), Y_RNA (79% identical), Y_RNA (78% identical), Y_RNA (77% identical), Y_RNA (76% identical), Y_RNA (75% identical), RNY3P4 (74% identical), RNY3P9 (74% identical), Y_RNA (74% identical), RNY3P14 (73% identical), and 90 more.